PLOD1 (procollagen-lysine,2-oxoglutarate 5-dioxygenase 1)
Diseases named in the same sentence as PLOD1 in open-access papers (continued):
Sharing a sentence is not in itself a finding about the gene and the disease.
tumor (49 papers, 2015 to 2026). "Inhibition of PLOD1 expression led to reduced tumor growth in vivo and downregulation of associated oncogenic markers, highlighting its potential as a therapeutic target in GC." (PMID 40740483, 2025). "Here, high-level PLOD1/2/3 expression was strongly linked to advanced pathological tumor stage and overall survival." (PMID 33134376, 2020). "Increased PLOD1/2/3 mRNA expression was significantly associated with advanced tumor stage, high pathological grade, and shorter progression-free and overall survival (all p<0.01)." (PMID 31446433, 2019). "This study thus identifies tumor expression of wild-type or mutated PLOD1/2/3 mRNA as a potential predictive biomarker for ccRCC patients and sheds light on the underlying molecular pathogenesis of ccRCC." (PMID 31446433, 2019). "Moreover, high expression of PLOD1 was significantly associated with tumor stage and presence of metastasis." (PMID 31199049, 2019). "However, studies on PLOD1 tumor-associated mutations are still relatively scarce." (PMID 39767559, 2024). "To compare the PLOD1 expression between tumors and normal tissues as fully as possible, we combined data from 33 tumor types from the TCGA and GTEx databases to analyze the differences in PLOD1 expression." (PMID 39767559, 2024). "Two other genes highly correlated with HPV gene expression, S100A9 and PLOD1, are involved in inflammation and tissue remodeling and important for tumor growth, invasion, and metastasis." (PMID 39193365, 2024). "The comparison shows that PLOD1–3 were overexpressed in STS tumor tissues compared to the normal tissue (p < 0.0001)." (PMID 35627171, 2022). "Through the HPA database, we found that three genes (ABCC9, AHNAK, and DIP2C) had low expression in patients with tumours, whereas eight genes (PLOD1, SLC3A2, RUNX2, RAD9A, CHMP4C, DARS2, CLIC3, and POU5F1) were highly expressed." (PMID 36685927, 2022). "The extreme limiting dilution assays also showed a reduction in tumor formation after PLOD1 knockout." (PMID 33420370, 2021). "PLOD1 also enhances tumor vitality, activity, and migration, and promotes the transformation of GBM into malignant mesenchymal subtypes." (PMID 35265665, 2021). "PLOD1 also enhanced tumor viability, proliferation, migration, and promoted MES transition while inhibited apoptosis." (PMID 33420370, 2021). "Transwell assays found that PLOD1 overexpression promoted tumor invasion, but the invasiveness of PN03-GSC and PN04-GSC was reversed after administration of the JSH-23." (PMID 33420370, 2021). "First, we used the MTS assays to detect the proliferation activity of tumor cells after PLOD1 knockout, and the absorbance values were significantly lower than those of the control group, confirming that PLOD1 knockout inhibits the proliferation of GSCs." (PMID 33420370, 2021). "We also found that the tumor formation rates increased after PLOD1 overexpression as measured by the extreme limiting dilution assays." (PMID 33420370, 2021). "So, it is of great significance to explore specific inhibitors of PLOD1 for preventing tumor progression." (PMID 34040895, 2021). "Transwell assays showed that PLOD1 overexpression markedly promoted tumor cell invasion and increased migration compared with controls." (PMID 33420370, 2021). "We then explored the possible downstream mechanisms of tumor-promoting effects of PLOD1, and GSEA analysis revealed enrichment of the NF-κB signaling pathway at higher PLOD1 expression." (PMID 33420370, 2021). "Tumor xenograft results also indicated that PLOD1 overexpression significantly promotes malignant behavior of tumors." (PMID 33420370, 2021). "In contrast, PLOD1 overexpression cell line PN03-GSC had a significantly larger tumor volume and a notable shorter median survival time than the empty vector control (mean survival: 42.6 ± 3.83 and 21 ± 4.69 days)." (PMID 33420370, 2021). "The remarkable association between PLOD1 (P = 0.009) and PLOD2 (P < 0.0001) expressions and tumor grade was observed." (PMID 33014843, 2020).
tumor (continued). "High PLOD1 expression was also related to a highly malignant tumor morphology, advanced stage, and metastasis." (PMID 31199049, 2019). "In order to explore the functional significance of PLOD1 on tumor progression, we examined the PLOD1‐mediated downstream genes and pathways." (PMID 31199049, 2019). "This suggests that PLOD1 interacts with tumor cells and tumor-infiltrating immune cells." (PMID 39767559, 2024). "In the tumor microenvironment, PLOD1 expression correlated positively with the infiltration level of various immunosuppressive cells (e.g., monocytes, macrophages and tumor-associated fibroblasts) and negatively with immune-killing cells (e.g., CD8+ T cells, B cells and CD4+ T cells)." (PMID 39767559, 2024). "In addition, we found that PLOD1 is involved in tumor development through lysine degradation, the PI3K-Akt signaling pathway, focal adhesion, ECM–receiver interaction and protein digestion and absorption." (PMID 39767559, 2024). "Similarly, high PLOD1 expression remained an unfavorable indicator for tumor patients in the DSS, DFS and PFS analyses." (PMID 39767559, 2024). "We hypothesized that PLOD1 might be involved in the remodeling or degradation of the extracellular matrix and might also play a role in tumor invasion." (PMID 39767559, 2024). "Through the HPA database, we found that three genes, namely ABCC9, AHNAK, and DIP2C, had low expression in patients with tumours, and eight other genes—PLOD1, SLC3A2, RUNX2, RAD9A, CHMP4C, DARS2, CLIC3, and POU5F1—were highly expressed in patients with tumours." (PMID 36685927, 2022). "Besides, we also found that hypoxic environments also enhanced the tumor-promoting effects of PLOD1." (PMID 33420370, 2021). "Besides, PLOD1 expressed higher in the core than the tumor’s outer margin according to the Ivy atlas." (PMID 33420370, 2021). "In addition, we used TUNEL assays to detect the effect of PLOD1 knockout on apoptosis in GSCs and showed that PLOD1 knockout significantly promoted apoptosis in tumor cells." (PMID 33420370, 2021). "However, hypoxia’s tumor-promoting effects were reversed after PLOD1 knockout, suggesting that PLOD1 is an important downstream gene of the tumor-promoting effects under hypoxic environment on GSCs." (PMID 33420370, 2021). "Furthermore, the expression levels of PLOD1–3 were positively correlated with the activities of tumor-infiltrating immune cells, including macrophages, neutrophils, CD4+ T cells, and dendritic cells." (PMID 33014843, 2020). "Abnormal expression of PLOD1–3 genes can promote tumor progression and metastasis, and it is reasonable to speculate that PLODs are the potential targets for HCC treatment." (PMID 33014843, 2020). "Even though they exhibited consistent tumor-normal dysregulation, five genes (COL12A1, CTSB, PLOD1, SPP1, and SULF1) were excluded from the final candidate list as they did not satisfy the meta-analysis criteria and exhibited loss of prognostic significance." (PMID 41451347, 2025). "While three genes (AHNAK, ABCC9, and DIP2C) were highly expressed in normal tissues, eight genes (CHMP4C, CLIC3, DARS2, PLOD1, POU5F1, RAD9A, RUNX2, SLC3A2) were highly expressed in tumour tissues." (PMID 36685927, 2022). "PLOD1, PLOD2, and PLOD3 were highly expressed in LGG tumor tissues compared to normal tissues (p < 0.01)." (PMID 35250490, 2022). "We further proved that the high expression levels of PLOD1 and PLOD2 were markedly correlated with higher tumor grade." (PMID 33014843, 2020). "The high expression levels of PLOD1 and PLOD2 genes were significantly correlated with higher tumor grades in HCC patients." (PMID 33014843, 2020). "A deeper investigation into the interaction mechanisms between SERPINH1, PLOD1, ITGA5, and ESM1, and how they collectively influence tumor biological behavior, may reveal potential therapeutic targets for novel treatment strategies." (PMID 40705756, 2025). "PLOD1 expression was positively correlated with ER, TNBC status, and tumor grade." (PMID 39068670, 2024).
tumor (continued). "The PLOD family members (PLOD1, PLOD2, and PLOD3) were overexpressed in HNSCC tumor tissue." (PMID 36820030, 2023). "These evaluations indicated that PLOD1, PLOD2, and PLOD3 might be high expressed in HNSCC tumor tissues compared with normal tissues (all p < 0.01)." (PMID 36820030, 2023). "Hence, we found that not only PLOD1 but also PLOD2 and PLOD3 were abundantly expressed in tumor tissues." (PMID 35250490, 2022). "Eight genes (SLC3A2, DARS2, DIP2C, PLOD1, RUNX2, ABCC9, AHNAK, and CLIC3) may be involved in the malignant transformation of tumours, and three genes (CHMP4C, POU5F1, and RAD9A) may have a protective effect in patients with tumours." (PMID 36685927, 2022). "DeLong’s test showed that PLOD1 was superior to PLOD2 in predicting tumor and normal outcomes, but the test was not statistically significant (p = 0.148); PLOD1 was significantly superior to PLOD3 (p ≤ 0.01)." (PMID 35265665, 2021). "Besides, it has been shown that hypoxic environment enhances PLOD1 and PLOD2 expression, and hypoxia, an important feature of GBM cells, has a role in promoting tumor cell growth, invasion, and MES transition, etc.." (PMID 33420370, 2021). "In the glycolysis pathway, PLOD1/2, FUT8 and TSTA3 are deregulated genes that participate in metabolism and glycolytic processes, which can influence the malignant transformation of cells, tumour development and metastasis." (PMID 32218455, 2020). "The expression of PLOD1 was upregulated in lysyl oxidase-like 4 (LOXL4) knockout xenograft tumor tissues and LOX4 knockdown could enhance tumor growth and metastasis through collagen-dependent extracellular matrix changes in TNBC." (PMID 31231467, 2019). "Molecular factors such as PTPRH, CPNE1, APLN, PLOD1, SPAG4, B7‐H3, and SIK2 have been shown to facilitate carcinogenesis and glycolysis via PI3K/AKT induction, whereas inhibitors of this pathway reduce glycolytic flux, diminish tumor growth, and increase sensitivity to anticancer drugs." (PMID 40740483, 2025). "Notably, several of these enzymes are druggable: for example, PLOD1 and PLOD2, which are involved in collagen crosslinking, can be targeted by specific inhibitors such as minoxidil, which disrupts collagen maturation and tumor-stroma interactions." (PMID 40034261, 2025).
connective tissue disorder (7 papers, 2010 to 2025). A disease involving the connective tissue. "The hereditary connective tissue disorder, first described by a US research group in 2011 and for which a commercial genetic test exists since 2013, is caused by a point mutation in the PLOD1 gene, inherited autosomal recessively." (PMID 35901076, 2022).
genetic disease (2 papers, 2022 to 2025). "Kyphoscoliotic Ehlers–Danlos syndrome (kEDS; OMIM225400) is a rare autosomal recessive genetic disease caused by variants in the PLOD1 gene." (PMID 35252061, 2022). "One of the genetic disorders of concern in warmblood horses is fragile foal syndrome (FFS), an autosomal recessive disease caused by a mutation in the PLOD1 gene (c.2032G>A)." (PMID 41497457, 2025).
PLOD1 also shares sentences with these, for which no sentence is quoted: lung adenocarcinoma (3 papers); atherosclerosis (2); diabetes (2); gastric adenocarcinoma (2); keratoconus (2); oral squamous cell carcinoma (2); ovarian carcinoma (2); renal cell carcinoma (2); abdominal aortic aneurysm (1); arteriosclerosis (1); arthrochalasia EDS (1); benign tumors (1); Bruck syndrome (1); cataract (1); cervical cancer (1); cholera (1); Cleidocranial dysplasia (1); dementia (1); dilated cardiomyopathy (1); Ehlers-Danlos syndrome, type 4 (1); Fabry disease (1); Familial adenomatous polyposis (1); familial thoracic aortic aneurysms (1); gastric intestinal type adenocarcinoma (1); Hearing impairment (1); Hyperglycemia (1); hypertrophic cardiomyopathy (1); idiopathic pulmonary fibrosis (1); immune deficiency (1); incontinentia pigmenti (1).
A further 29 diseases each share a sentence with PLOD1 in 1 paper.